RNU6-387P (RNA, U6 small nuclear 387, pseudogene)
Gene: Small nuclear RNA gene on chromosome 1 (67,417,214 to 67,417,318, forward strand). Ensembl gene ENSG00000223263.
Homologues: Orthologues: chimpanzee U6 (99% identical), macaque U6 (92% identical). Paralogues in human: RNU6-144P (84% identical), RNU6-1263P (83% identical), RNU6-16P (83% identical), RNU6-21P (83% identical), RNU6-333P (83% identical), RNU6-812P (83% identical), RNU6-1 (82% identical), RNU6-1179P (82% identical), RNU6-11P (82% identical), RNU6-1251P (82% identical), RNU6-15P (82% identical), RNU6-2 (82% identical), and 1285 more.